INS (insulin)
Diseases named in the same sentence as INS in open-access papers (continued):
Sharing a sentence is not in itself a finding about the gene and the disease.
erectile dysfunction (12 papers, 2007 to 2025). Persistent or recurrent inability to achieve or to maintain an erection during sexual activity. "Two-sample Mendelian randomization (TSMR) was used to examine the causal effect of antidiabetic drugs (including metformin, insulin and gliclazide) on erectile dysfunction." (PMID 39247921, 2024). "Other reasons for aborting were initiation of insulin treatment (n = 2), erectile dysfunction (n = 1) and hospitalisation due to cardiac event (n = 1)." (PMID 17570858, 2007). "There was no significant causal relationship between insulin use and erectile dysfunction [Beta: 3.0730; OR:21.6071 (95% CI:0.24-1942.38); p-value: 0.1806).Leave-one-out, MR-Egger, and MR-PRESSO analyses produced consistent results." (PMID 39247921, 2024). "There is no causal relationship between the use of insulin and erectile dysfunction." (PMID 39247921, 2024).
escherichia coli infection (12 papers, 2016 to 2024). Infection with the organism Escherichia Coli. "Examples include toxoplasmosis, pathogenic Escherichia coli infection, insulin resistance, and Toll and IMD pathway." (PMID 37048440, 2023). "The increased production of PGE2 raised the possibility of an autocrine-paracrine loop in INS-1E cells after E. coli infection, causing insulin secretion reduction." (PMID 27631977, 2016). "Also, the results of KEGG enrichment analysis showed that the target genes are mainly involved in pathways of the ribosome, pathogenic Escherichia coli infection, and the insulin signaling pathway." (PMID 35069738, 2022). "The results demonstrate that PGE2 production is responsible for insulin release dysfunction after E. coli infection." (PMID 27631977, 2016). "The results obtained demonstrated that cPLA2 and iPLA2 play a key role in insulin secretion process after E. coli infection." (PMID 27631977, 2016). "Several of the treatments employed in this study, such as L. monocytogenes or E. coli infections and genetic activation of the Toll pathway in the fat body, have been shown to interfere with the insulin signalling pathway and subsequently decrease nutrient storage or growth." (PMID 35538789, 2022). "However, in the presence of Escherichia coli infection, it may result in a misleadingly high insulin concentration measured by an immunoassay because of cross-reactions." (PMID 35324747, 2022). "Instead, insulin secretion, significantly reduced after long-term infection, is restored in presence of NS-398 and L-798106, further confirming the PGE2 role after E. coli infection." (PMID 27631977, 2016). "The results obtained in this study show that, after short-term E. coli infection, PLA2 activities were increased and pancreatic cells continue to secrete insulin that results in even higher amounts in the E. coli-infected cells compared to uninfected ones." (PMID 27631977, 2016). "When, after long-term E. coli infection, INS-1E no longer respond to high concentrations of glucose, the siRNA-iPLA2 transfection allows a response to glucose with consequent insulin secretion from INS-1E cells to be restored, even if to a lesser extent compared to that of non-infected cells." (PMID 27631977, 2016).
Graves disease (12 papers, 2011 to 2024). Graves' disease is an autoimmune disorder that leads to overactivity of the thyroid gland (hyperthyroidism).It is caused by an abnormal immune system response that causes the thyroid gland to produce too much thyroid hormones. "These alterations do not mirror the pronounced variations typically seen in conditions, such as Graves’ disease or primary hypothyroidism, which have been the focus of most previous research on insulin production and action." (PMID 39203787, 2024). "When NAMPT leukocyte expression was used as a dependent variable, simple regression analysis found associations with TRAb, fasting insulin level, HOMA-IR, Graves’ disease, and Graves’ orbitopathy." (PMID 26767650, 2016). "Graves' disease has been reported to increase the intestinal absorption of carbohydrates and production of hepatic glucose from glycogen due to hepatic insulin resistance." (PMID 21492449, 2011). "Interestingly, although our patient had a personal history of Graves’ disease, IRAb has not been reported in patients with Graves’ disease, in contrast to the close association between Graves’ disease and Hirata’s disease caused by insulin autoantibodies." (PMID 36387920, 2022).
hemorrhage (12 papers, 2014 to 2025). Loss of blood from the vascular compartment to the exterior or into nonvascular body space as a result of rupture or severance of the blood vessels. "We found that higher fasting insulin levels were associated with the presence of intraplaque hemorrhage (fully adjusted odds ratio (OR) per 1-s.d. increase in insulin level: 1.38 (95% CI: 1.09–1.74)) (model 2)." (PMID 31958313, 2020). "It is important to note that, in the current study, although LZ and OZ had relatively similar insulin levels after hemorrhage, the low level of insulin most likely caused greater consequences in the insulin‐resistant OZ." (PMID 25472607, 2014). "Irisin-induced improvements to cardiac functions following a hemorrhage here are associated with an increase in insulin sensitivity, suggesting that insulin sensitivity could be an additional factor in the regulation of cardiac performance." (PMID 36297305, 2022). "We retrospectively analyzed 514 consecutive patients with cerebral small vessel disease (CSVD)-related haemorrhage, comparing the differences in novel inflammatory and insulin resistance indices between patients with CAA and HA." (PMID 38769356, 2024). "The results suggest that irisin protects against damage from a hemorrhage through the modulation of insulin sensitivity." (PMID 36297305, 2022). "Pentobarbital was shown to prevent the elevation in glucose in response to transport in goats, to impair the hypoglycemic effect of insulin in rats and to markedly blunt sympathoadrenal release of noradrenaline in response to hemorrhage in rats." (PMID 33746780, 2021). "The sympathetic control of insulin secretion has been shown to be primarily regulated by α2‐adrenergic activation, resulting in decreased levels of insulin after hemorrhage." (PMID 25472607, 2014). "Sympathetic nerve activity (SNA) has been shown to regulate insulin secretion through α2‐adrenergic activation, resulting in decreased levels of insulin after hemorrhage." (PMID 25472607, 2014). "Although the precise molecular mechanism by which irisin mediates insulin sensitivity in hemorrhages is currently unknown, the improved insulin sensitivity by irisin plays a key role in protecting against hemorrhage." (PMID 36297305, 2022). "This suggests that other factors such as muscle glycogen, muscle glucose uptake, and insulin's effect on these may play a role in the resultant plasma glucose levels after hemorrhage." (PMID 25472607, 2014).
Hypercalcemia (12 papers, 2005 to 2025). An abnormally increased calcium concentration in the blood. "Similarly, murine models revealed that PTH infusion and consequent hypercalcemia were associated with higher glucose levels and similar insulin levels, while both PTH and calcium positively correlated with glucose levels only in rats who received PTH injections." (PMID 40283231, 2025). "Subjects with hypercalcemia had lower insulin levels during hypoglycemia episodes compared to the persons with normal serum calcium (p < 0.001)." (PMID 38928056, 2024). "The effect of leucine on hypercalcemia might, therefore, be explained by increased insulin release, leading to increased renal absorption of phosphate." (PMID 31600911, 2019). "However, serum C-peptide level at 0.5 h and serum insulin level at 1 h was higher in patients with hypercalcemia than in patients with normal serum Ca levels in the oral glucose tolerance test (OGTT), although the differences were not statistically significant." (PMID 35698198, 2022). "Thus with WT mice treated with SPR4-peptide (binds to and inactivates ASARM-motif and peptide), the dramatic increase in 1.25(OH)2D3, hypercalcemia and reduced sclerostin may have helped to counteract the reduced osteocalcin resulting in normal glucose and insulin levels." (PMID 24839967, 2014).
hyperparathyroidism (12 papers, 2012 to 2025). Hyperfunction of the parathyroid glands resulting in the overproduction of parathyroid hormone. "Hyperparathyroidism (in any of its clinical presentations) is associated with altered carbohydrate metabolism and a disturbed insulin secretion or impaired cellular sensitivity." (PMID 25886602, 2015). "Some studies have shown that the use of ketoacids and/or essential amino acids associated to protein restriction improves the sensitivity to insulin and hyperparathyroidism and is compatible with the maintenance of the nutritional state." (PMID 23227299, 2012).
hypogonadotropic hypogonadism (12 papers, 2014 to 2025). Abnormal ovarian or testicular function due to insufficient hormonal stimulation from the hypothalamic-pituitary axis. "Male obesity-associated secondary hypogonadism (MOSH) involves increased levels of leptin, insulin, proinflammatory cytokines, and estrogen, which contribute to functional hypogonadotropic hypogonadism." (PMID 39801930, 2024).
kidney cancer (12 papers, 2011 to 2025). Primary or metastatic malignant neoplasm involving the kidney. "GLP-1RA was associated with an increased risk of kidney cancer as compared to metformin, whereas it is reduced compared to insulin." (PMID 40282969, 2025). "Kidney cancers showed an increased risk with GLP-1RA treatment relative to that with metformin (HR, 1.54; 95% CI 1.27-1.87) but a decrease relative to insulin (HR, 0.76; 95% CI 0.64-0.91)." (PMID 38967919, 2024). "KCNJ15 is known to participate in insulin secretion, nervous system diseases, gastric acid secretion, kidney cancer, and esophageal squamous cell carcinoma." (PMID 33633772, 2020). "Moreover, coffee consumption may reduce the risk of kidney cancer by improving insulin sensitivity." (PMID 21406107, 2011). "It found a significant reduction in the risk of several cancers among GLP1R agonist users compared to insulin users, but no clear benefit compared to metformin, and even a potential increased risk of kidney cancer." (PMID 39777709, 2025).
mitochondrial diabetes (12 papers, 2014 to 2026). "In mitochondrial diabetes, a hereditary disorder of mitochondrial functions causes impaired insulin secretion." (PMID 29942356, 2018). "In mitochondrial diabetes, apoptosis of β-cells caused by mitochondrial stress plays an important role in impaired insulin secretion." (PMID 29942356, 2018). "Mitochondrial diabetes can result from either impaired insulin secretion or reduced insulin sensitivity." (PMID 41323015, 2025). "Impaired insulin secretion occurs in mitochondrial diabetes, a hereditary disorder of mitochondrial functions." (PMID 29942356, 2018). "Mitochondrial diabetes usually leads to dysfunction of pancreatic islet beta-cells due to their poor ability to resist oxidative stress induced by mitochondrial chain dysfunction and to a consequent defect in insulin secretion." (PMID 35341481, 2022). "Other than insulin injection, treatments have not been established for mitochondrial diabetes, although several studies have shown that coenzyme Q10 (CoQ10) has therapeutic effects on mitochondrial diabetes." (PMID 29942356, 2018).
muscle atrophy (12 papers, 2013 to 2026). The loss of muscle tissue due to inactivity or disease. "Inhibiting the effects of myostatin/activin also improves insulin sensitivity, reduces systemic inflammation and improves skeletal muscle atrophy in disease models." (PMID 36458537, 2022). "Skeletal muscle atrophy is characterized by the reduction in muscle mass, fiber cross-sectional area, protein content, and strength, leading to increased fatigability and insulin resistance." (PMID 31731814, 2019). "Muscle atrophy is defined as reduced muscle fiber cross-sectional area, protein content, muscle strength, and insulin sensitivity." (PMID 31717643, 2019). "Myostatin inhibitors have been intensively studied as pharmaceutical targets for muscle atrophy and mice treated with anti-myostatin antibodies have increased muscle mass and improved muscle insulin sensitivity." (PMID 28222718, 2017). "Muscle atrophy in critically ill patients could also be attenuated by intensive insulin therapy, suggesting that glycemia control is an effective way to protect against muscle proteolysis." (PMID 30533176, 2018).
sexual dysfunction (12 papers, 2010 to 2025). Disturbances in sexual desire and the psychophysiologic changes that characterize the sexual response cycle and cause marked distress and interpersonal difficulty.
Barrett esophagus (11 papers, 2013 to 2026). Esophageal lesion lined with columnar metaplastic epithelium which is flat or villiform. "Previous studies have found that higher circulating levels of certain metabolic and inflammatory biomarkers, including leptin, glucose, insulin, C-reactive protein, interleukin 6, and soluble tumor necrosis factor receptor 2, are associated with an increased risk of esophageal adenocarcinoma." (PMID 40917762, 2025). "Calorie restriction reduced glycemia, IGF-1 and the IGF-1/IGFBP3 ratio, and improved insulin sensitivity in patients with Barrett’s esophagus (BE)." (PMID 37298551, 2023). "These alterations were associated with the down-regulation of the insulin/IGF-1 and ERK signaling pathways, which, in turn, decreased the risk of esophageal adenocarcinoma development." (PMID 37298551, 2023). "Visceral obesity may promote EAC by directly affecting gastroesophageal reflux disease and Barrett’s esophagus (BE), as well as a less reflux-dependent effect, including the release of pro-inflammatory adipokines and insulin resistance." (PMID 35409299, 2022). "Visceral obesity (VO) may promote EAC via both directly impacting on gastro-esophageal reflux disease and Barrett's esophagus, as well as via reflux-independent effects, involving adipokines, growth factors, insulin resistance, and the microbiome." (PMID 33777773, 2021). "Importantly, the insulin/IGF system is able to influence the risk of Barrett’s esophagus and of esophageal adenocarcinoma, although there is no full agreement about this." (PMID 27187365, 2016).
brain injury (11 papers, 2012 to 2024). Acute and chronic (see also brain INJURIES, CHRONIC) injuries to the brain, including the cerebral hemispheres, CEREBELLUM, and brain STEM. "Elevated plasma insulin levels and severe traumatic brain injury (TBI) can increase the risk of DVT." (PMID 38553747, 2024). "Last year, a paper was published showing that intranasal administration of insulin to rats with brain trauma inhibits autophagic processes and thus increases the viability of neurons in the brain." (PMID 39057034, 2024). "In a rodent model of ischemic brain injury, insulin and glucagon improved poststroke outcome in animal models by decreasing glutamate in the circulation and cerebrospinal fluid." (PMID 33510613, 2020). "This randomized control trial of insulin treat-ment in which patients with traumatic brain injury received at least 50% of their nutritional needs via parenteral rout, showed benefit in terms of anti HSP27 titres." (PMID 24711895, 2014). "Guidelines from the Brain Trauma Foundation and the European Brain Injury Consortium highlight the association of hyperG with worse prognosis after severe brain trauma, but these documents do not specify which glucose level should be considered as a trigger for initiating insulin therapy." (PMID 22400022, 2012). "Despite numerous studies on glucose metabolism in traumatic brain injured patients or in overall trauma populations, as mentioned, very little data is available on insulin resistance in major trauma patients without brain injury." (PMID 23031544, 2012).
cholestasis (11 papers, 2012 to 2024). Impairment of the bile flow caused by obstruction within the liver, or outside the liver in the bile duct system. "Modification of cholesterol and lipoprotein on cholestasis by bile duct ligation surgery is known; also, high concentration of plasma insulin and low concentration of glucose have been reported for this model." (PMID 30875780, 2019). "AMPK is a critical signaling pathway involved in inhibiting hepatic de novo lipogenesis and increasing fatty acid oxidation and insulin sensitivity, but the controversial role of this signaling in AMPK-FXR crosstalk, which induces cholestasis and hepatotoxicity, has been reported." (PMID 35277054, 2022).
colorectal adenoma (11 papers, 2012 to 2023). An adenoma that arises from the colon or rectum. "A meta-analysis including 16 studies and 14,007 patients found that higher levels of insulin were significantly associated with increased risk of colorectal adenomas." (PMID 35256755, 2022). "Insulin significantly increases the risk of colorectal adenoma in T2DM patients (OR:1.43), however in this analysis due to lack of data we could not report data on stratified analysis by duration of insulin use duration of DM or age." (PMID 29383018, 2018). "Insulin significantly increased the risk of colorectal adenoma (OR= 1.43, p=0.002)." (PMID 29383018, 2018). "In conclusion, our meta-analysis indicates that metformin is associated with a reduction in risk of colorectal adenoma incidence in individuals with T2DM, compared with insulin treatment which significantly increases the risk of colon adenoma." (PMID 29383018, 2018). "Few studies have evaluated IGFBP-1 and C-peptide or insulin in relation to colorectal adenomas and cancer and the results are inconsistent." (PMID 22950808, 2012). "Then the insulin recipient patients had a risk of colorectal adenoma compared with those who did not." (PMID 29383018, 2018). "The aim of this study was to determine the associations of IGFBP-1, insulin, and C-peptide (a surrogate biomarker of pancreatic insulin secretion), with colorectal adenoma (adenomatous polyps) in the Diet and Health study IV, in a majority White cohort and whether these associations vary by gender." (PMID 22950808, 2012). "Thus, IGFBP-1 levels may influence colorectal adenomas and cancer development via two mechanisms: inhibition of the proliferative actions of insulin and IGF, and promotion of apoptosis." (PMID 22950808, 2012). "Thus, higher circulating insulin levels may promote colorectal adenomas and cancer through increased proliferation or reduced apoptosis." (PMID 22950808, 2012).
dry eye (11 papers, 2019 to 2026). "Topical insulin has been reported to improve dry eye symptoms in diabetic patients, inducing IGF-1-mediated corneal nerve regeneration and corneal epithelial proliferation." (PMID 38744994, 2024).